GRK5 (G protein-coupled receptor kinase 5)
Diseases named in the same sentence as GRK5 in open-access papers (continued):
Sharing a sentence is not in itself a finding about the gene and the disease.
atherosclerosis (6 papers, 2013 to 2022). A disease characterized by the build-up of fatty material and calcium deposition in the arterial wall resulting in partial or complete occlusion of the arterial lumen. "GRK5 would be an ideal target to be therapeutically activated since GRK5−/−ApoE−/− mice have increased atherosclerosis." (PMID 23690662, 2013). "Indeed, enhanced GRK5 activity has been associated with favorable, β-blocker treatment-like outcomes in human CHF with attenuated atherosclerosis and with better cardiac function in humans/CHF patients." (PMID 32326036, 2020). "GRK5 may, thus, represent a possible target for the development of novel therapeutic strategies mitigating atherosclerosis." (PMID 29773828, 2018). "A possible impact of GRK5 on atherosclerosis was suggested in in vitro and in vivo studies." (PMID 29773828, 2018). "Additionally, based on previous in vitro and rodent data, GRK5 was suggested to be involved in the pathophysiology of atherosclerosis, though, both pro-atherogenic and anti-atherogenic activities were indicated." (PMID 29773828, 2018).
Sepsis (6 papers, 2012 to 2024). Sepsis is defined as life-threatening organ dysfunction caused by a dysregulated host response to infection. "GRK2 and GRK5 expression are enhanced in sepsis patients and in rodent models of severe sepsis, which are associated with impaired migration of neutrophils and enhanced susceptibility to secondary microbial infection." (PMID 22745844, 2012). "It was shown that GRK5 deficiency leads to decreased cytokine levels, decreased thymocyte apoptosis and immune suppression, and reduced plasma corticosterone levels, leading to sepsis-induced mortality even in the presence of antibiotics in both endotoxemia and polymicrobial sepsis models." (PMID 33806057, 2021). "Conversely, sepsis-associated inflammation is reduced in GRK5-deficient mice, suggesting opposite effects of GRK2 and GRK5 on myeloid cells and/or effects in other cell types." (PMID 33466410, 2021). "It was shown that GRK2 and GRK5 play a notable role in the pathogenesis of human sepsis by regulating neutrophil chemotaxis, and modulate the outcomes of septic shock via the NF-κB1p105-TPL2-MEK-ERK pathway." (PMID 33806057, 2021). "Regarding transcripts of the adrenergic pathway, sepsis decreased the α-adrenergic receptor (α-AR) and phospholipase C beta 4 (PLCB4) expression and increased G protein-coupled receptor kinase 5 (GRK5) that inhibits adrenergic pathways, only in OVR females." (PMID 35322092, 2022).
colon cancer (5 papers, 2011 to 2022). "G-protein coupled receptor kinase-5 is known to regulate proliferation and chemokine gene expression in human colon cancer epithelial cells." (PMID 29156751, 2017). "Our findings suggest that TIG1-mediated growth suppression of colon cancer cells is mediated, at least in part, through GRK5." (PMID 21575264, 2011). "We have recently demonstrated both TIG1A and TIG1B isoforms inhibited cell growth and induced the expression of G protein-coupled receptor kinase 5 (GRK5) in colon cancer cells." (PMID 22126303, 2011). "Because PGE2 stimulates TOPFLASH and CREB reporter activities through the PGE2 receptor subtype 2, EP2, in DLD-1 colon cancer cells, the effects of GRK5 expression on PGE2-stimulated TOPFLASH and CREB reporter activities in EP2-transfected HCT116 cells were analyzed." (PMID 22126303, 2011). "TIG1 suppressed PGE2-stimulated Wnt and cAMP signaling pathways in colon cancer cells through GRK5." (PMID 22126303, 2011). "Expression of both TIG1A and TIG1B isoforms upregulated GRK5 expression and inhibited the growth of HCT116 and SW620 colon cancer cells." (PMID 22126303, 2011). "In conclusion, both TIG1A and TIG1B suppressed PGE2-stimulated colon cancer cell proliferation, β-catenin nuclear localization, β-catenin/TCF transactivation, and cAMP/CREB signaling through expression of GRK5." (PMID 22126303, 2011). "The extent of growth reversion and inhibition of GRK5 expression was largely similar in TIG1A expressing cells transfected with GRK5 siRNA, suggesting that GRK5 plays a pivotal role in TIG1-mediated growth inhibition of HCT116 colon cancer cells." (PMID 21575264, 2011).
prostate carcinoma (5 papers, 2016 to 2025). A carcinoma that arises from epithelial cells of the prostate gland. "In these naturally low GRK5 expressing tissues, upregulation of GRK5 is increasing aggressiveness of glioma and is associated with increased proliferation of prostate cancer." (PMID 34109182, 2021). "GRK5 has been implicated as having a role in regulating lung, brain and prostate cancer cell growth." (PMID 32363002, 2020). "Taken together, these results propose GRK5 as a key contributor to the growth and metastasis of prostate cancer." (PMID 27326393, 2016). "Notably, in prostate cancer models, GRK5 knockdown reduced PD-L1 expression by inhibiting STAT3 phosphorylation." (PMID 40722845, 2025). "Both studies identify GRK5 as an oncogene in prostate cancer." (PMID 40722845, 2025). "The study published in Cancer Research posits that GRK5 facilitates prostate cancer invasion through the regulation of actin dynamics, while the Journal of Urology article suggests that GRK5 promotes prostate cancer proliferation by modulating the cell cycle and tumor suppressor genes." (PMID 40722845, 2025). "To date, GRK5 has been shown to play a role in the pathogenesis of lung, brain and prostate cancer." (PMID 32363002, 2020). "Loss of GRK5 in NSCLC and prostate cancer cell lines also results in cell cycle arrest." (PMID 32363002, 2020). "Moreover, in a xenograft model of human prostate cancer, GRK5 silencing reduced tumor growth, invasion and metastasis." (PMID 27326393, 2016).
Hepatic steatosis (4 papers, 2014 to 2025). Steatosis is a term used to denote lipid accumulation within hepatocytes. "In the present study, we examined the therapeutic effects of a GRK inhibitor, GRK5-IN-2, on adiposity, hepatic steatosis, and systemic metabolism in diet-induced obese mice." (PMID 40666930, 2025). "Previous studies using whole-body Grk5 knockout mice reported the development of severe hepatic steatosis compared to WT controls." (PMID 40666930, 2025). "The whole body Grk5 KO mice exhibit impaired insulin signaling, which contributes to severe hepatic steatosis." (PMID 40666930, 2025). "Collectively, these findings indicate that GRK5-IN-2 may mitigate liver steatosis by favoring fatty acid utilization over triglyceride synthesis." (PMID 40666930, 2025). "Together, these findings suggest that GRK5 inhibition selectively modulates hepatic lipid metabolism without altering systemic metabolic parameters, highlighting GRK5 as a potential therapeutic target for fatty liver disease." (PMID 40666930, 2025). "Our findings suggest that GRK5-IN-2 attenuates hepatic steatosis by suppressing triglyceride synthesis and promoting mitochondrial fatty acid oxidation, potentially through inhibition of GRK2 alongside GRK5." (PMID 40666930, 2025).
non-small cell lung carcinoma (4 papers, 2018 to 2022). A group of at least three distinct histological types of lung cancer, including non-small cell squamous cell carcinoma, adenocarcinoma, and large cell carcinoma. "GRK5 was found to facilitate proliferation and progression and be related with the regulation of cell cycle in non-small-cell lung cancer." (PMID 34116604, 2021).
medulloblastoma (3 papers, 2017 to 2022). A malignant, invasive embryonal neoplasm arising from the cerebellum. "A recent research article demonstrated that crosstalk among Wip1, CXCR4 and GRK5 promote aggressive phenotype of a medulloblastoma in children." (PMID 28915621, 2017).
myocardial infarction (3 papers, 2022 to 2025). Gross necrosis of the myocardium, as a result of interruption of the blood supply to the area, as in coronary thrombosis. "Conversely, cardiomyocyte-specific GRK5 ablation diminished the early immune cell infiltration in the heart, improved contractility and reduced mortality post-myocardial infarction." (PMID 33560342, 2022). "Notably, GRK5 has been shown to promote tissue repair and survival following myocardial infarction through regulation of inflammatory and transcriptional programs." (PMID 41515937, 2025). "The exact function of GRK5 in myocardial infarction is still unclear." (PMID 41515937, 2025). "Thus, GRK5 in cardiac myofibroblasts is an important molecule that promotes inflammation and fibrosis to ameliorate the damage after myocardial infarction." (PMID 36633120, 2023). "G‐protein‐coupled receptor kinase 5 (GRK5) is highly expressed in cardiac myofibroblasts and initiates inflammation through nuclear factor‐κB activation, leading to an increase in the expression levels of fibrosis‐related genes in the acute phase of myocardial infarction." (PMID 36633120, 2023).
thyroid cancer (3 papers, 2016 to 2022). "Indeed, several thyroid cancer types (DTC) have high levels of cAMP compared with normal thyroid tissue (NTT), and it has been demonstrated that this is associated with a reduction of the expression of GRK5 gene and protein levels." (PMID 27326393, 2016). "Finally, we predicted and verified 8 GRSDMs in adrenocortical carcinoma (ACC), rectum adenocarcinoma (READ), uveal Melanoma (UVM), thyroid carcinoma (THCA), and predicted 4 GRSDMs (F2RL3, DGKB, GRK5, PIK3R6) which were sensitive to 12 potential drugs." (PMID 35885996, 2022). "Also in thyroid cancer cells, GRK5 has negative effects on tumor growth, due to its ability to down-regulate GPCRs activity, in particular TSH-receptor activity." (PMID 27326393, 2016).
triple-negative breast carcinoma (3 papers, 2019 to 2022). An invasive breast carcinoma which is negative for expression of estrogen receptor (ER), progesterone receptor (PR), and human epidermal growth factor receptor 2 (HER2). "Sunitinib, a kinase inhibitor, was found to inhibit downstream CDC42 and RHO kinases 1 (ROCK1) functions by targeting G Protein-Coupled Receptor Kinase 5 (GRK5) to modulate the motility of triple-negative breast cancer cells." (PMID 34572451, 2021). "In order to further investigate the function of GRK5 in triple-negative breast cancer (TNBC), MDA-MB-231 cells stably expressing a doxycycline inducible shGRK5 were generated (termed MDA-MB-231 TRIPZ-shGRK5 in the following)." (PMID 31664083, 2019). "An in silico Kaplan Meier analysis revealed that GRK5 and GRPR overexpression reduces the distant metastasis free survival in triple-negative breast cancer (TNBC) patients." (PMID 31664083, 2019).
Cognitive impairment (2 papers, 2010 to 2016). Abnormal cognition is characterized by deficits in thinking, reasoning, or remembering. "The deficiency of GRK5, on the other hand, impairs presynaptic M2 autoreceptor desensitization, which leads to a reduced acetylcholine release, axonal/synaptic degenerative changes, and associated amnestic, mild cognitive impairment." (PMID 20730384, 2010). "Therefore, this study warrants such human population-based studies with the objective of determining whether GRK5 deficiency exists in cognitively impaired or vulnerable populations with not only mild cognitive impairment and AD but also others such as OSA and Parkinson’s dementia." (PMID 27193825, 2016). "However, even if the strength of the GRK5 deficiency is not sufficient to cause cognitive impairment, it is sufficient to make the animals more vulnerable to cognitive impairment from additional insults, such as the over-expression of Swedish APP in the GAP mice." (PMID 27193825, 2016).
coronary heart disease (2 papers, 2015 to 2022). "In this study, we evaluated whether cardiomyocyte GRK5 plays a critical role during ischemic heart disease in a mouse animal model." (PMID 33560342, 2022). "However, it is still unknown if GRK5 is involved in the establishment and development of ischemic heart disease." (PMID 33560342, 2022). "However, the role of GRK5 in ischemic heart disease is still unknown." (PMID 33560342, 2022).
dementia (2 papers, 2018 to 2025). Loss of intellectual abilities interfering with an individual's social and occupational functions. "It has also been proposed that the involvement of GRK5 in dementia-related conditions is likely associated with its potent role in regulating neurite outgrowth that is required for optimal learning and memory function." (PMID 30618771, 2018). "Continued investigation will likely reinforce the importance of GRK5 as a therapeutically-exploitable systems-level controller and coordinator of the cardiovascular-dementia pathological axis." (PMID 30618771, 2018).
glioblastoma (2 papers, 2020 to 2021). The most malignant astrocytic tumor (WHO grade IV). "GRK5 functions as oncogenes in glioblastoma (GBM), prostate, pancreas, non-small-cell lung, and breast cancers." (PMID 35223984, 2021). "In non-small cell lung cancer (NSCLC) and glioblastoma multiforme (GMB), GRK5 is highly expressed in primary patient specimens and depletion of GRK5 results in reduced cell growth." (PMID 32363002, 2020).
infarction (2 papers, 2018 to 2025). A localised pathological necrosis of tissue resulting from obstruction of the blood supply usually by a thrombus, an embolus, or vascular torsion. "GRK5 expression is dynamically regulated following myocardial injury and may increase as a part of an adaptive or compensatory response during the post-infarction phase." (PMID 41515937, 2025).
kidney cancer (2 papers, 2022 to 2025). Primary or metastatic malignant neoplasm involving the kidney. "We observed that the mRNA expression level of ETV4 was significantly increased and the expression levels of SH2B3, FATE1, GRK5, MALL, HRH2, SEMA3G and SLC10A6 were decreased prominently in kidney cancer cells when compared with HK2 cell line." (PMID 36059531, 2022). "Furthermore, we detected the mRNA and protein expression levels of 8 epi-PCGs (ETV4, SH2B3, FATE1, GRK5, MALL, HRH2, SEMA3G and SLC10A6) in 4 human kidney cancer cell lines (786-O, A498, Caki-1 and ACHN) and the normal human renal tubular epithelial cell line HK2." (PMID 36059531, 2022).
lymph node metastasis (2 papers, 2021). "In addition, GRK5/ACTC1 co-expression was associated with the following factors: histology, FIGO stage, lymph node metastasis, intraperitoneal metastasis, intestinal metastasis, vital status, differentiation grade, and ascites with tumor cells." (PMID 35223984, 2021).
malaria (2 papers, 2017 to 2019). Malaria is a serious and sometimes fatal disease caused by a parasite that commonly infects a certain type of mosquito which feeds on humans. "We found that all Bubi individuals possessed the malaria-resistant allele of the ACKR1 and CD36 genes, in addition to certain variations in other genes such as G6PD, ATP2B4, GRK5, and IL-10." (PMID 30841922, 2019).
Myocardial fibrosis (2 papers, 2020 to 2023). "Fibroblast-specific deletion of GRK5 attenuates myocardial fibrosis and hypertrophy after chronic Ang II infusion or ischemic injury." (PMID 37122736, 2023).
osteosarcoma (2 papers, 2020 to 2021). A usually aggressive malignant bone-forming mesenchymal neoplasm, predominantly affecting adolescents and young adults.
Parkinson disease (2 papers, 2016 to 2018). A progressive degenerative disorder of the central nervous system characterized by loss of dopamine producing neurons in the substantia nigra and the presence of Lewy bodies in the substantia nigra and locus coeruleus. "Several reports show that GRK5 is also involved in Parkinson disease, due to its ability to phosphorylate the α-synuclein, modulating dopamine-up-take." (PMID 27326393, 2016). "Moreover, in a model of Parkinson disease, the nuclear accumulation of GRK5 inhibits gene transcription of apoptosis regulator bcl-2, probably increasing HDAC activity." (PMID 27326393, 2016).
amyloidosis (1 paper, 2018). A disorder characterized by the localized or diffuse accumulation of amyloid protein in various anatomic sites. "From genetic deletion mouse models (i.e., GRK5-KO) it has been shown that GRK5 functionality is associated with severe hippocampal dysfunction (loss of neurosynaptic proteins and axonal swelling) as well as increased amyloidosis." (PMID 30618771, 2018).
Arthritis (1 paper, 2021). Inflammation of a joint. "This study is the first to elucidate the characteristics of GRK5 expression in human synovium and the effect of GRK5 knockout on the development of arthritis in a murine model of CAIA." (PMID 34006987, 2021). "Divided into front and hind paws, each arthritis score was also significantly lower in GRK5 knockout mice than in WT mice." (PMID 34006987, 2021). "In a CAIA model, GRK5 knockout mice had significantly suppressed development of arthritis, with less severe synovitis and cartilage degeneration compared to WT mice." (PMID 34006987, 2021). "Additional analysis at different time points might provide further information about the functional effects of GRK5 on the pathogenesis of arthritis." (PMID 34006987, 2021). "Collectively, these findings suggested that GRK5 functions as a positive intermediator of LPS-stimulation in macrophages, therefore, GRK5 knockout significantly delays the onset of arthritis and suppresses the initial progression down to a mild level in a CAIA." (PMID 34006987, 2021). "In a murine model of collagen antibody-induced arthritis, arthritis scores and serum IL6 production of GRK5 knockout (GRK5-/-) mice were significantly lower than those of wild-type mice." (PMID 34006987, 2021).
cerebrovascular diseases (1 paper, 2014). "Previous studies have reported that GRK5 and GPCR (class A) are related to cardiovascular and cerebrovascular diseases." (PMID 24594703, 2014).
colorectal carcinoma (1 paper, 2019). A malignant epithelial neoplasm that arises from the colon or rectum and invades through the muscularis mucosa into the submucosa. "A previous study showed that TIG1 induces expression of GRK5, subsequently decreasing cell proliferation and increasing cell death in colorectal carcinoma cells." (PMID 31886233, 2019).
differentiated thyroid carcinoma (1 paper, 2021). Differentiated thyroid carcinoma (DTC), also known as papillary or follicular thyroid carcinoma, is a slow-growing malignancy usually presenting in adults as an asymptomatic thyroid mass. "GRK2, but not GRK5, is more highly expressed in differentiated thyroid carcinoma than normal thyroid tissue, and is involved in the rapid desensitization of thyroid-stimulating hormone receptor (TSHR), which desensitization can be further inhibited by GRK5." (PMID 33806057, 2021).
dilated cardiomyopathy (1 paper, 2018). Cardiomyopathy which is characterized by dilation and contractile dysfunction of the left and right ventricles. "GRK5 expression is also increased in dilated cardiomyopathy and volume-overloaded human left ventricle, whereas the expression of GRK3 remains stable in dilated cardiomyopathy and is slightly induced in patients with right ventricular volume overload." (PMID 30538631, 2018).
Enterococcus faecalis infection (1 paper, 2022). A bacterial infection induced by Enterococcus faecalis which is the most prevalent species (along with Enterococcus faecium) cultured from humans, accounting for more than 90% of clinical isolates. "Noticeably, the cytokine expression consecutive to Escherichia coli infection was impaired in zebrafish embryos for the orthologous GRK5, and in D. melanogaster, the susceptibility of infections with Enterococcus faecalis infection is increased by RNAi silencing of Grpk2." (PMID 35742941, 2022).